IRF1 (interferon regulatory factor 1)
Diseases named in the same sentence as IRF1 in open-access papers (continued):
Sharing a sentence is not in itself a finding about the gene and the disease.
tumor (continued). "The protein expression of IFNAR1 was significantly correlated with those of IRF1 and PDL1 in both tissues but with those of ATF4 and eIF2α only in the tumor tissue." (PMID 30305853, 2018). "The protein levels of IRF1, eIF2α, ATF4, and PDL1 in the tumor tissues of the all subject group were significantly correlated with each other and formed a cluster in dendrogram." (PMID 30305853, 2018). "To investigate the functional interplay of IRF-1 and XAF1 in tumor suppression, we initially characterized their interrelationship in stress-induced apoptosis." (PMID 30042418, 2018). "Collectively, this study identifies a novel mechanism of XAF1-mediated tumor suppression, uncovering XAF1 as a feedback coactivator of IRF-1 under stressful conditions." (PMID 30042418, 2018). "Expression levels of IRF-1 and XAF1 correlate tightly in both cancer cell lines and primary tumors, and XAF1-induced tumor regression is markedly attenuated in IRF-1-depleted tumors." (PMID 30042418, 2018). "The protein levels of ATF4 and PDL1 had the closest proximity in both tissues, and they formed a cluster with those of IRF1, eIF2α, and IFNAR1 in the tumor tissue." (PMID 30305853, 2018). "To delineate the possible implication of the IRF-1−XAF1 axis alteration in tumorigenesis, we characterized expression status of IRF-1 and XAF1 in established cell lines and primary tumor tissues." (PMID 30042418, 2018). "The protein levels of IRF1, eIF2α, and ATF4 were consistently correlated in the tumor tissues but to various extents in the normal ones." (PMID 30305853, 2018). "Several of these genes, including IFI27, IFITM1, IRF1, STAT1, IF16, and TAP1, are known to possess potent anti-proliferative and tumor suppressive properties." (PMID 29176033, 2017). "Defects in this IFNγ-IRF1 regulated APM pathway allow tumors to escape immune surveillance, facilitate tumor development in animal models that include lung tumors, and are associated with resistance to anti-PD-1 immunotherapy in melanoma." (PMID 28977839, 2017). "Compared with the control uninfected chickens, IRF1 and STAT1 levels were decreased in the tumor samples." (PMID 27252695, 2016). "Expression of IRF1 as well as p27Kip1, a tumor suppressor induced by IRF1, was downregulated by RasV12 transfection, indicating that Ras/MEK activation suppresses expression and function of IRF1." (PMID 27508303, 2016). "Thus, apoptosis may be one of the means through which IRF-1 affects tumor growth." (PMID 27191889, 2016). "Importantly, the in vitrofindings were reproduced in vivo as IRF-1 deficient animalsinoculated i.p with L929 cells were extremely susceptible to tumor growth and theirmacrophages did not produce NO, while WT mice killed L929 tumor cells and theirmacrophages produced high levels of NO." (PMID 25659093, 2015). "IRF1, which was the first identified IRF, acts as a critical regulatory protein of the inflammatory response and functions as a tumor suppressor that is involved in cell cycle progression and apoptosis." (PMID 25980475, 2015). "This set of experiments indicates that IRF1 expression in tumor cells is required for BV6-induced cytokine secretion by tumor cells and recruitment of monocytes towards tumor cells." (PMID 25501823, 2014). "Also, IRF1 is important for the DNA damage-induced apoptosis of mitogenically activated mature T lymphocytes These studies suggested that IRF1 might harbor tumor suppressor activity." (PMID 25893139, 2013).
tumor (continued). "We previously demonstrated that IL-27 inhibits the tumor growth of B16F10-WSX-1 cells through the WSX-1/STAT1 and IRF-1 pathway." (PMID 24155891, 2013). "Along the same line, IRF1, NF-kB p65, and MHC-I are coordinately expressed in vivo in tumor lesions, their nuclear absence and presence neatly segregating between high-grade and low-grade NB, respectively." (PMID 23071666, 2012). "STAT1, a transcription factor upstream of IRF1 and mediator of IFN signaling, is also considered a tumor suppressor gene." (PMID 22295238, 2011). "In contrast, injection of mc-oriP-IFNγ resulted in obvious IRF-1, p21 and BAK staining only in the EBV-positive C666-1 tumor." (PMID 21573215, 2011). "Interferon regulatory factor-1 (IRF-1) is another factor that falls into this category, in that it plays an important tumor suppressive role in a wide variety of human neoplasias." (PMID 18682805, 2008). "Moreover, transcriptomic and Q-PCR analyses showed increased expression of Stat1, Zbp1, Parp14, Irf1, and Tifa along with decreased Eif4e2 in the SOR treatment group compared to the tumor control group." (PMID 42194025, 2026). "Analysis of tumors from ApcMin/+/Ptpn13fl/fl/Vil-CreERT2 (APV) mice showed that Ptpn13 knockout, induced by TAM treatment, significantly upregulated the expression of IRF1, LMP2, TAP1, TAP2, H2-D1, H2-K1, and B2M and also increased the surface levels of MHC-I complex on tumor cells." (PMID 41486293, 2026). "At the same time, STAT1 forms a complex with interferon regulatory factor 1 (IRF1), upregulates ACSL4, and promotes the integration of polyunsaturated fatty acids (such as arachidonic acid) into the phospholipids of tumor cell membranes, significantly increasing lipid peroxidation sensitivity." (PMID 40535125, 2025). "IRF1 was downregulated in HER2+ tumor FB2 fibroblast and smooth muscle cells and not detected in a cluster of relatively rare epithelial cells indicated as EPI2." (PMID 40862725, 2025). "While the full MAC assembly can cause cell lysis, sub-lytic MAC deposition—facilitated by elevated C7—activates intracellular pathways in tumor cells, including Ca2+- and G-protein-mediated signals, and transcription factors such as EGR1, IRF1, AREG, and CXCL1." (PMID 40806542, 2025). "This pathway has been confirmed in both genotoxic stress and radiotherapy models, where activation of ATM/ATR signaling increases PD-L1 expression via IRF1, contributing to attenuation of IFN-driven T-cell responses and promoting short-term survival of stressed tumor cells." (PMID 41373427, 2025). "We observed in both patients that IDO1 positive tumor cells displayed a higher percentage of GLI and STAT1/IRF1 double positive cells than IDO1 negative tumor cells." (PMID 39962447, 2025). "In these factors, like Interferon Regulatory Factor 1 (IRF1) and Nuclear factor, erythroid 2 like 2 (NFE2L2) have been reported to function in the anti-tumor capacity, while HIF-1 alpha (HIF1A) and Signal transducer and activator of transcription 3 (STAT3) to support tumor growth and immune evasion." (PMID 40230843, 2025). "The IFNγ pathways shared the downstream IRF1 and STAT1 molecules that bound with the promoters of PD-L1 and CXCL10, enhancing the efficacy of anti-PD1/PD-L1 inhibitors and boosting T-cell infiltration in the tumor microenvironment." (PMID 40149259, 2025). "Apoptosis and immunological responses are controlled by the IRF (Interferon Regulatory Factors) family and members such as IRF1 and IRF8 are crucial for anti-tumor immunity because they activate T cells and dendritic cells, promoting the release of pro-inflammatory cytokines." (PMID 41155227, 2025). "In summary, the results from the PDX model demonstrate that our MNF system, loaded with IRF-1, significantly increases ROS levels in tumor tissues, enhances cellular nuclear damage, and exhibits no harm to normal tissues." (PMID 38693181, 2024).
tumor (continued). "Additionally, IRF1 was found to antagonize IRF2 binding to the IRE promoter element in PD-L1, leading to the upregulation of PD-L1 in the tumor microenvironment." (PMID 38999981, 2024). "To further validate the involvement of the PROS1-AXL axis in the upregulation of macrophage MMP9 via MICA+ tumor cells, we introduced the AXL inhibitor cabozantinib to macrophages stimulated via recombinant human PROS1 protein and co-cultured with IRF1+ Huh7 cells." (PMID 38254761, 2024). "SCRIPro could accurately predicts well-known master regulators including SPI1, IRF1, FLI1, and STAT2 for mono/macrophages, GATA3, RUNX3, SMARCA4, JUND, and MYB for T-cells, PAX5, BCL2, and IRF4 for B and tumor B-cells." (PMID 39024032, 2024). "These evidences illustrate that IRF1, IRF4, IRF5, IRF6, and IRF8 may be candidate tumor-suppressors in CRC." (PMID 39384770, 2024). "Without a doubt, IRF1 can be considered one of the most significant mediators of IFNγ action, both in tumor cells and in the cells of their microenvironment." (PMID 38396830, 2024). "Additionally, IRF1 promoted the migration of NK and NKT cells, as well as CD4+ and CD8+ T cells, into the tumor microenvironment." (PMID 38396830, 2024). "IRF1 was found to be able to reduce the expression of the CXCL9 chemokine gene, which, among its other properties, is important for attracting T lymphocytes to the tumor site." (PMID 38396830, 2024). "Mechanically, PTA reinforces the anti-tumor ability of Th9 cells primarily through upregulating interleukin (IL)-1β and subsequently activating the downstream STAT1/IRF1 pathway, which could be effectively blocked by intercepting IL-1β signaling." (PMID 38760861, 2024). "We performed qRT-PCR on mRNA extracted from snap-frozen tumor tissue, measuring transcripts for IFNγ, to indicate response to ICI, and interferon regulatory factor 1 (IRF1), to indicate whether downstream IFNγ signaling is disrupted." (PMID 38130991, 2023). "Yet, cellular signaling pathways that mediate pro- and anti-tumor effects of IRF1 are not fully elucidated." (PMID 37094077, 2023). "Furthermore, another study incorporated interferon regulatory factor 1 (IRF-1), which is a tumor suppressor gene that regulates the expression of target genes such as MHC I, IL-15, and IFN-α." (PMID 37681880, 2023). "Thus, we found that PARP14 pharmacological antagonism or silencing in tumour cells enhanced STAT1 phosphorylation and expression of STAT1 target gene products, including IRF1 responsible for the expression of many IFNγ signalling genes but also PARP14 itself." (PMID 37752135, 2023). "Interestingly, we found that IRF1, STAT1, STAT2, and STAT3 were all significantly downregulated in Scissor+ tumor cells compared to Scissor− and background tumor cells." (PMID 37021816, 2023). "Gene expression profiling of MM cells treated with ARd results in upregulation of IRF1, which is a tumor suppressor that inhibits BCL2 transcription, but increases expression of caspases and enhancement of mitochondrial-mediated tumor cell apoptosis." (PMID 36672426, 2023). "Moreover, we found that RAB13 silencing enhanced the expression of interferon regulatory factors-1 (IRF1) and IRF4, which are vital factors mediating tumor immunity." (PMID 36901767, 2023). "A recent study has shown that the RSI is associated with immune response in a large sample of tumours, which is not unexpected given the inclusion of STAT1 and IRF1." (PMID 37444614, 2023).
tumor (continued). "Downstream IFN-Ɣ pathway is inducing STAT1 activation achieving various biological functions such as IRF1 expression and tumor growth regulation, but STAT1 activation is also described for enhancing tumor progression through chronic inflammation responsible for controversial therapeutic implication." (PMID 37726776, 2023). "IFNγ receptor genes IFNGR1, IFNGR2 and the downstream effector IRF1 have been reported to be expressed on a PNET cell line QGP-1, and IFNγ treatment could inhibit tumor growth and induce apoptosis in vitro, indicating a direct anti-PNET effect of IFNγ." (PMID 38020179, 2023). "Therefore, mutations and deletions of proteins related to this pathway on tumor cells, such as JAK1 and JAK2, STAT1, and IRF1, the IFNγ receptor chain, can lead to resistance to immune checkpoint inhibitors." (PMID 36185620, 2022). "In fact, a short form of IRF1, lacking exon 7, appears during Th1 differentiation and its expression is increased in tumor settings and during exposure to TGF-β." (PMID 35406498, 2022). "GO analysis highlighted terms related to angiogenesis, cell migration, cell proliferation, and inflammation, while transcription factor motif enrichment analysis additionally suggested an activation of interferon (IRF1) and TGF (SMAD2) signaling in tumor-draining LN fLECs." (PMID 35892863, 2022). "IRF1 is a well‐known transcription factor to regulate tumour cell PD‐L1 expression by binding to CD274 promoter, and BRD4 is another key mediator of both tumour cell constitutive and IFN‐γ‐stimulated CD274 transcription." (PMID 35083874, 2022). "An explanation for these results could be the downregulation of PD-L1 on tumour cells, mediated indirectly by oncogenic EGFR signalling via IRF1." (PMID 36010935, 2022). "In addition, we confirmed CD11b+/Ly6Chi monocytes attributed the highest expression of Irf1, a key ISG regulator, in tumour samples by flow cytometry." (PMID 35986006, 2022). "Contrary to the HEK293T and MCF-7 cells, BCA2 was unable to interact with IRF1 in the non-tumor and ER– cancer cells, which is consistent with a lack of BCA2-dependent IRF1 up-regulation." (PMID 34589482, 2021). "Thus, we accessed the exoRBase database to show higher mRNA expression levels of IRF1 and MFNG in exosomes from human blood, compared to that from multiple tumor tissues." (PMID 34277600, 2021). "The expression of JUN, CDK1, IRF1, and STAT1 was significantly higher in the RSI-Low tumours." (PMID 34078917, 2021). "In addition to down-regulating NF-κB, we uncovered that BCA2 activates interferon regulatory factor 1 (IRF1), a well-known tumor suppressor and immunomodulatory transcription factor, although the mechanism by which BCA2 achieves this remains to be elucidated." (PMID 34589482, 2021). "To test whether the mechanism behind the in vivo effects of EGCG was similar to that observed in vitro, we analyzed B16F10 tumor samples for STAT1 and IRF1 expression." (PMID 34832863, 2021). "The consideration of microenvironment for tumor seems essential regarding the expression of a gene as TAP1 as its regulation may be determined by proteins like STAT1 and IRF1." (PMID 34047812, 2021). "Thus, while IRF2 expression is downregulated in many different tumor types suggesting potential tumor suppressor roles, other studies proposed pro-tumorigenic functions for IRF2, including via antagonism of IRF1 functions." (PMID 33668131, 2021). "Moreover, the N-cadherin antagonist ADH-1 promotes the antitumor response of tumor infiltrating lymphocytes (TILs), interfering with the JAK/STAT pathway: CXCL11 and IRF1 were upregulated after using ADH-1." (PMID 34830179, 2021). "Although BCA2’s enzymatic activity is dispensable to activate IRF1 in HEK293T and MCF-7 cells, and we were unable to detect a physical interaction between BCA2 and IRF1 in the non-tumor cell line, it is plausible that BCA2 contributes to such regulation to some extent." (PMID 34589482, 2021).
tumor (continued). "The oncoprotein HPV16 E6 directly binds with IRF-1 tumour suppressor, but not IgG used as a negative control." (PMID 33076322, 2020). "Interferon-gamma produced by activated T cells binds to its receptor on tumor cells and determines STAT1 activation and transcription of IRF1/7 which in turn binds to the CD274 promoter, increases PD-L1 transcription and, ultimately, the expression on tumor cells." (PMID 33114576, 2020). "Moreover, the results of immunoblotting showed that the tumor PD-L1 protein level was highly increased, and the phosphorylation of STAT1 and its downstream transcription factor IRF1 was significantly increased in the resected tumors from the DAC and OXP group." (PMID 32079180, 2020). "The knockdown of IRF1 in macrophages induces their pro-tumor activity regarding to hepatocellular carcinoma cell lines HepG2 and SMMC-7721, promoting proliferation and invasion of tumor cells." (PMID 32486098, 2020). "Public databases indicate that IRF-1 expression is significantly decreased in multiple tumour tissues, including GC, compared with that in nontumour adjacent tissues." (PMID 31186404, 2019). "Moreover, our results also demonstrate that the type II interferon IFN-γ, which is mediated by IRF-1, can attenuate MIR17HG expression in GC cells and therefore further links the tumour immune response to cancer cell metastasis." (PMID 31186404, 2019). "Moreover, FOXM1c expression was positively correlated with IRF1 expression in ESCC cell lines and tumour specimens." (PMID 30485581, 2019). "Globally, these results indicate that the Irf1−/− mice respond to AOM/DSS treatment with an increase in epithelial proliferation compared to controls, as well as an increase in ISCs, and this, at a time (D26) preceding tumor emergence." (PMID 31827213, 2019). "The CD274 promoter contains two interferon regulatory factor-1 (IRF-1) binding sites, and previous work has shown that type 1 and type 2 interferons (IFN) induce PD-L1 expression on T cells, B cells, endothelial cells, epithelial cells, and tumor cells." (PMID 29844327, 2018). "Skipping of exon 2 in mutant IRF-1 is associated with an absent DBD and loss of the tumor-suppressing action of the encoded protein." (PMID 29599126, 2018). "On this basis, we assessed whether XAF1 inhibits tumor cell migration and invasion by blocking p65/RelA-mediated MMP9 transcription through IRF-1 induction." (PMID 30042418, 2018). "The protein levels of STAT1 and IRF1 were significantly correlated in the normal but not in the tumor tissues." (PMID 30305853, 2018). "Moreover, 14 of 18 (77.8%) low XAF1 tumors and 14 of 20 (70%) low IRF-1 tumors displayed low IRF-1 and XAF1, respectively, indicating that XAF1 and IRF-1 levels correlate tightly in both normal and tumor tissues." (PMID 30042418, 2018). "Wound healing and Matrigel assays revealed that IRF-1 and XAF1 strongly suppresses TNF-induced tumor cell migration and invasion and this effect is abrogated by depletion of XAF1 and IRF-1, respectively, indicating TNF-driven tumor malignancy is impaired by the IRF-1−XAF1 interplay." (PMID 30042418, 2018). "The significant correlations between the protein levels of IRF1 and eIF2α or ATF4 in the tumor tissues may result from high ER stress which trigger UPR in cancer." (PMID 30305853, 2018). "Nuclear IRF-1 staining was also observed in stromal cells in close proximity IRF-1-positive tumor cells, but this expression was not quantified in the current assay." (PMID 28331615, 2017). "Additionally, to estimate immune cell prevalence we used the average expression of the lymphocyte-specific genes GZMB, PRF1, CXCL13, IRF1, IKZF1, and HLA-E in each tumor sample." (PMID 27959926, 2016).